MMP2 (matrix metallopeptidase 2)
Diseases named in the same sentence as MMP2 in open-access papers (continued):
Sharing a sentence is not in itself a finding about the gene and the disease.
Aortic dissection (11 papers, 2009 to 2025). Aortic dissection refers to a tear in the intimal layer of the aorta causing a separation between the intima and the medial layers of the aorta. "Mean values of MMP-2 were lower in patients with acute aortic dissection (group A) and higher in patients with acute myocardial ischemia (group D)." (PMID 19886986, 2009). "Excessive LDH could enhance lactate synthesis in vascular smooth muscle cells (VSMCs) and affect the phenotypic transformation of VSMCs and the expression of MMP2/9, which leads to the development of aortic dissection." (PMID 37198546, 2023). "LINC01605 is upregulated in a mouse model of aortic dissection and participates in the cellular processes of migration, proliferation and autophagy associated with aortic dissection by modulating the expression of genes such as SGK1, MMP‐2, MMP‐9, α‐SMA, SM22α, LC3B and p62." (PMID 41294029, 2025). "The expression of MMPs, particularly MMP2 and MMP9, combined with inflammatory cell infiltration, are also characteristics of aortic dissection pathogenesis." (PMID 40680508, 2025). "Nine proteins (Lumican, FGL1, PI16, MMP9, FBN1, MMP2, VWF, MMRN1, and PF4) related to the pathogenesis of aortic dissection were identified by David /Ease and String techniques as candidate biomarkers for verification test." (PMID 35910577, 2022). "It has been reported that when aortic dissection occurs, the serum levels of MMP1, MMP2, MMP3, MMP8, and MMP13 are increased, and the expression of MMP9 in the cytoplasm of smooth muscle cells in the aortic wall is enhanced." (PMID 35463768, 2022). "Ang II, NA, MMP-2, MMP-9 of the aorta sample obtained during operation from aortic dissection patients were detected by High Performance Liquid Chromatography and ELISA and compared with controls." (PMID 24194850, 2013).
cerebral infarction (11 papers, 2012 to 2024). An ischemic condition of the brain, producing a persistent focal neurological deficit in the area of distribution of the cerebral arteries. "MMP-2/MMP-9 aggravates BBB dysfunction caused by cerebral infarction by degrading ZO-1 and claudin-5, all TJ proteins." (PMID 33584203, 2020). "Single nucleotide polymorphisms that cause protein structural defects or affect TIMP-2 transcription efficiency can cause cerebral infarction or cerebral hemorrhage by affecting the balance between TIMP-2 and MMP-2." (PMID 29435135, 2018). "At the same time, Claudin-5 and occludin were degraded by MMP2, the BBB was destroyed and the size of cerebral infarction increased." (PMID 35959401, 2022). "In this study, vx-765 treatment enhanced the expression levels of TIMP-1 and TIMP-2 but reduced the expression levels of MMP-1, MMP-2, MMP-3, and MMP-9 proteins after cerebral infarction." (PMID 33584203, 2020). "Several matrix-methaloproteinases such as MMP2, MMP7, MMP9 and MMP12, were up-regulated after cerebral infarct." (PMID 23284893, 2012). "Many methalloproteinases showed highly altered expression, including MMP2 and MMP7 at 3 d after cerebral infarct, as well as MMP9 and MMP12 in the acute (24 h) phase." (PMID 23284893, 2012).
diabetic cardiomyopathy (11 papers, 2012 to 2025). Diabetic cardiomyopathy is a disorder of the heart muscle in people with diabetes. "According to our theory, this early MMP-2 downregulation is reverted during the progression of diabetic cardiomyopathy, causing an increased deposition of degraded collagen and the development of the fibrosis and apoptotic cell death." (PMID 33050121, 2020). "Several studies in vivo demonstrated that cardiac fibrosis in diabetic cardiomyopathy is associated with a decrease in MMP-2 expression/activity." (PMID 22713251, 2012). "Moreover, in db/db mice, miR122-5p overexpression was associated with diabetic cardiomyopathy and MMP-2 regulation." (PMID 39857629, 2024). "Indeed cardiovascular disorders are associated with decreased expression of MMP-2, which has been shown to be a direct mediator of cardiac fibrosis in diabetic cardiomyopathy." (PMID 25501750, 2014). "In addition, because it is unclear whether intracellular isoform of MMP-2 is the cause or the result of diabetic cardiomyopathy, further direct or indirect suppression studies should be conducted." (PMID 31461499, 2019). "On the other hand, a previous study reported that inhibition of MMP-2 activity leads to cardiac fibrosis in diabetic cardiomyopathy." (PMID 32354131, 2020). "In the onset of diabetic cardiomyopathy, mitochondrial impairment in cardiomyocytes is characterized by the dysregulation of the different MMP-2 isoforms." (PMID 33050121, 2020). "Our results, demonstrated that ALA treatment ameliorated cardiac dysfunction, decreased LV Type I and III collagen deposition, reduced TIMP-2 and increased MMP-2 activity in STZ-induced diabetic cardiomyopathy." (PMID 22713251, 2012). "Conversely, reduced Mmp2 expression may lead to disrupted collagen turnover, impaired cardiac metabolism, and ultimately fibrosis progression as observed in diabetic cardiomyopathy." (PMID 40869420, 2025). "Our study showed that the intracellular FL-MMP-2 isoform was localized to the sarcomeres, which suggests intracellular MMP-2 is also induced in diabetic cardiomyopathy and that it caused cardiac contractile dysfunction during early stage DM CMP without inducing ECM fibrosis or LV remodeling." (PMID 31461499, 2019). "The researchers hypothesized that high glucose stimulation induced the expression of full-length MMP-2 and N-terminal truncated MMP-2 in vitro and in diabetic heart models, suggesting a potential link between Mmp2 isoforms and diabetic cardiomyopathy." (PMID 39769454, 2024).
dry eye (11 papers, 2012 to 2025). "Long-term dry eye is associated with increased expression of inflammatory factors, such as TNF-α, MMP-2, MMP-9, ICAM-1, and VCAM-1, on the ocular surface." (PMID 30002412, 2018). "MMP-2 transcripts were undetectable in the samples obtained from normal subjects and those obtained from dry eye subjects." (PMID 26904272, 2016). "Long-term dry eye is associated with increased expression of inflammatory factors, such as tumor necrosis factor-alpha (TNF-α), matrix metalloproteinase (MMP-2, MMP-9), intercellular adhesion molecule-1 (ICAM-1), and vascular cell adhesion molecule-1 (VCAM-1) in the ocular surface." (PMID 30002412, 2018). "ALA can downregulate the expression of MMP‐2 and MMP‐9 in corneal epithelial cells and activate the antioxidant status of the ocular surface, preventing dry eye;." (PMID 40207422, 2025). "Although the mRNA level of matrix metalloprotease (MMP)-2 was comparable, MMP-9 was significantly decreased after the Cact-3 treatment in the dry eye mouse model." (PMID 35563597, 2022). "Given that PEDF and MMP-2 and -9 coexist in the dry eye milieus, dosing with exogenous PEDF and 29-mer to overwhelm the enzymatic activity of MMP-2 and -9 and suppress the production of MMP-9 from CECs would be beneficial for DED therapy." (PMID 36201200, 2022). "Matrix-metalloproteinases (MMPs), specifically MMP-2 (gelatinase A) and MMP-9 (gelatinase B), have certain effects on wound healing, ocular surface disease, dry eye, and keratoconus." (PMID 28280636, 2017). "We postulate that 17β-estradiol upregulates MMP-2 and MMP-9 production in the lacrimal gland and MMP-9 production in the conjunctival epithelium and thus increases the activity of MMP-2 and MMP-9 in tears of dry eye subjects." (PMID 26904272, 2016). "The tear concentrations of MMP-2 and MMP-9 in the dry eye group were significantly greater than those in the control group (P < 0.001)." (PMID 26904272, 2016). "Tear MMP-2 and MMP-9 concentrations (P < 0.001), as well as the MMP-9 mRNA expression in conjunctival samples (P = 0.02), were significantly higher in dry eye subjects than in controls." (PMID 26904272, 2016). "Consistent with previous findings, we also found that the tear concentrations of MMP-2 and MMP-9 in dry eye subjects were significantly higher than those in controls." (PMID 26904272, 2016). "Matrix-metalloproteinases (MMPs), specifically MMP-2 (gelatinase A) and MMP-9 (gelatinase B), are in tears and also in corneal tissue during wound healing and in ocular surface disease, including dry eye and keratoconus." (PMID 23977185, 2013). "Also, notably, the previous literature showed elevated expressions of both MMP-2 and MMP-9 in dry eyes, and both MMP-2 and MMP-9 have been shown to preferentially degrade basement membrane components and are implicated in corneal epithelial wound healing." (PMID 38534403, 2024). "Expression of HO-1, COX-2, MMP-2, MMP-9, and IL-6 increased markedly in the dry eye group." (PMID 23049824, 2012). "Additionally, the presence of pro-MMP-2 was increased in tear samples from all animals with dry eye (treated and non-treated), compared to the control." (PMID 33057006, 2020). "Therefore, we postulate that 17β-estradiol may have effects on the promotion of inflammation in the lacrimal gland and conjunctival epithelium and may increase the activity of MMP-2 and MMP-9 in tears of patients with dry eye." (PMID 26904272, 2016). "Increased MMP-2 and MMP-9 production has been observed in the tear fluid collected from patients with systemic dry eye and from those with nonsystemic dry eye." (PMID 26904272, 2016).
liver disease (11 papers, 2011 to 2025). "MMP-2 is secreted by activated HSCs; elevated levels of MMP-2 and its proenzyme have been observed in various liver diseases." (PMID 21849046, 2011). "MMP-2, MMP-9, and FGF-19 levels were dysregulated among the HIV/HBV–co-infected, and 11% of HIV/HBV–co-infected had evidence of undiagnosed advanced liver disease." (PMID 39471521, 2025). "In conclusion, non‐specific MMP inhibition with minocycline and relatively specific MMP‐2/MMP‐9 inhibition with SB‐3CT ameliorated liver cirrhosis and portal hypertension‐related derangements." (PMID 34647412, 2021). "Active MMP-2 and its activity calculated as the ratio of active to latent MMP-2 correlated strongly with all degradation and formation markers in severe fibrosis, pointing out that ECM markers display the turnover of ECM in liver disease." (PMID 23908632, 2013). "Conclusively, MMP-2 mRNA expression was upregulated during all stages of fibrosis; however, only active MMP-2 was detected in the later stages, i.e., during the resolution of fibrosis, suggesting the role of MMP-2 in the resolution of hepatic IRI (and possibly other liver diseases)." (PMID 32414178, 2020). "Moreover, treatment with MSCs significantly decreased col1 transcripts, with beneficial trends of profibrogenic gene expression of tissue inhibitor of metalloproteinases-1 (TIMP-1) and MMP-2, 8, and 9, confirming that MSC infusions significantly attenuated T2DM-induced liver disease." (PMID 31747961, 2019). "Minocycline, a nonselective MMP inhibitor, and 3B‐SCT, an MMP‐2 and MMP‐9 inhibitor, significantly attenuated portal hypertension in rats with BDL‐induced liver cirrhosis." (PMID 34647412, 2021). "Thus, MMP-2, MMP-9 and TNF-α could not be correlated with the progression of liver disease." (PMID 26464613, 2015).
pancreatic adenocarcinoma (11 papers, 2004 to 2023). "This was in consistent with many previous studies where an association between MMP2, pancreatic adenocarcinoma invasion, and metastasis was detected." (PMID 36013494, 2022). "We have previously shown that the Src family kinase inhibitor pyrazolopyrimidine (PP2) inhibits pancreatic adenocarcinoma cellular invasiveness in association with dephosphorylation of the prototype Src family kinase, c-Src, and suppression of MMP-2 and MMP-9 activities." (PMID 15316565, 2004). "We identified seven prognostic genes (MET, DYNLL2, CDK1, TNFSF10, PIP5K1C, MSLN, GKN1) and validated that their related proteins, such as EGFR and MMP2, have a significant impact on the prognosis of pancreatic adenocarcinoma." (PMID 37370756, 2023). "Peak SUV, main lesion SUVmax, serum MMP-2, and the tumor glycolytic activity can be considered as good predictors in pancreatic adenocarcinoma patients’ PFS." (PMID 36013494, 2022). "However, MMP-2 is predominantly expressed by the tumor stroma in hepatocellular and pancreatic adenocarcinoma." (PMID 27175590, 2016). "The aim of the study was to evaluate the expression of MMP-2, MMP-7, and MMP-9 in normal ducts, tumor pancreatic adenocarcinoma cells, and peritumoral stroma in correlation with clinicohistopathological parameters." (PMID 27429508, 2016). "Therefore, the aim of our study was to evaluate the immunohistochemical expressions of MMP-2, MMP-7, and MMP-9 in the normal pancreas, pancreatic adenocarcinoma tumor cells, and stromal cells in correlation with clinicopathological features." (PMID 27429508, 2016).
rectal cancer (11 papers, 2000 to 2025). A primary or metastatic malignant neoplasm that affects the rectum. "Kokelaar (2021), reported that the expression of MMP2 (matrix metallopeptidase 2) is significantly associated with extramural venous invasion (EMVI), a specific type of vascular invasion in rectal cancer." (PMID 40650042, 2025). "Rectal cancer specimens expressed both pro (72 kDa) and active (62 kDa) forms of MMP-2 but only the pro form of MMP-9 (92 kDa)." (PMID 10732772, 2000). "Increased type-IV collagenase activity (MMP-2 and MMP-9) following preoperative RTX in rectal cancer was recently discovered." (PMID 19323831, 2009). "We designed this study to determine any differences in the expression of MMP-2, MMP-9 and uPA system between colon and rectal cancer tissues." (PMID 16916471, 2006). "Moreover, preoperative radiotherapy leads to a significant increase in the levels of MMP-2 and MMP-9 in rectal cancer tissues without their correspondent increase in normal mucosa." (PMID 30336548, 2018).
acute coronary syndrome (10 papers, 2014 to 2024). Signs and symptoms related to acute ischemia of the myocardium secondary to coronary artery disease. "Both MMP-9 and MMP-2 were shown to be released from platelets into coronary circulation during acute coronary syndrome, showing the potential association of MMPs and the development of acute coronary syndrome." (PMID 28770228, 2017). "Similarly, elevated MMP2 levels have been previously associated with an increased risk of death in patients with acute coronary syndrome and several cancers." (PMID 37803875, 2023). "Disturbed equilibrium of the metalloproteinase/tissue inhibitors system, destabilization of atherosclerotic plaque, and acute coronary syndrome (ACS) in patients are caused by increased expression of MMP-2 and MMP-9 metalloproteinases and their tissue inhibitor (TIMP-2)." (PMID 32486345, 2020). "Both MMP-2 and MMP-9 are associated with plaque vulnerability and cap rupture, predisposing to acute coronary syndrome." (PMID 36996033, 2023). "Fundamentally, platelets from patients with acute coronary syndromes release matrix metalloproteinase-2 (MMP-2), a major source of glycocalyceal damage, while, in turn, MMP-2 induces further platelet activation." (PMID 37511046, 2023). "Elevated MMP-2 activity has been determined to be an independent mortality marker in patients with acute coronary syndrome." (PMID 36142876, 2022). "Because MMPs participate in rupture of atherosclerotic plaques, we decided to check whether chronically elevated plasma glucose increases the expression and release of MMP-2 and MMP-9, hence accelerating the risk for acute coronary syndromes." (PMID 28770228, 2017). "Increased peripheral blood MMP-2 and MMP-9 in acute coronary syndrome (ACS) may be useful as noninvasive tests for detection of plaque vulnerability." (PMID 32486345, 2020).
acute myeloid leukemia (10 papers, 2012 to 2025). Acute myeloid leukemia (AML) is a group of neoplasms arising from precursor cells committed to the myeloid cell-line differentiation. "MMP‐2 and MMP‐9 are assumed to be particularly important for cell transmigration, and the association of cell surface between MMP‐2, MMP‐9 and integrins has been implicated in the progression and growth of chronic myeloid leukaemia and acute myeloid leukaemia cells." (PMID 33566449, 2021). "The expression of serum MMP-2 and von Willebrand factor (vWF) in patients with acute myeloid leukemia (AML) at different risks and their predictive value and prognostic impact were investigated." (PMID 35935313, 2022). "In addition, the activity of MMP‐2 and MMP‐9 may be related to an aggravated course of acute myeloid leukaemia, implying an interplay between MMP‐2/MMP‐9 and T‐ALL." (PMID 33566449, 2021). "In the present study, changes in mRNA expression levels of selected metalloproteinase genes (MMP2, MMP9, and MMP16) in acute myeloid leukemia were evaluated." (PMID 34035811, 2021). "The obtained results show that the expression of MMP2 and MMP16 genes is reduced while the expression of MMP9 is unchanged in patients with acute myeloid leukemia." (PMID 34035811, 2021). "Secreted matrix metalloproteinases (MMP)-2 and MMP-9 and membrane-anchored aminopeptidase-N/CD13 are abnormally expressed in human acute myeloid leukaemia (AML)." (PMID 25246708, 2014). "The cells of people with acute myeloid leukemia have a lower relative gene expression level of the MMP2 and MMP16 but no MMP9 compared to patients without cancer." (PMID 34035811, 2021). "The expression level of the MMP2, MMP9, and MMP16 genes does not depend on the presence of cytogenetic changes in cancer cells and gender and age of patients with acute myeloid leukemia." (PMID 34035811, 2021).
astrocytic tumor (10 papers, 2013 to 2025). A glial tumor of the brain or spinal cord showing astrocytic differentiation. "MMP-2 expression was associated with shorter overall survival in patients with grade II-IV astrocytic tumors (HR 1.60; 95% CI 1.03–2.48; p = 0.036)." (PMID 28234925, 2017). "Also, in the same study, Ramachandran and colleagues found MMP-2 expression to be associated with shorter overall survival in patients with grade II–IV astrocytic tumors." (PMID 33227903, 2020). "The Sp1 binding site is essential for basal transcriptional activity of both MMPs as only ∼10% and ∼30% of transcription activity is observed when Sp1 at −102 on MT1-MMP in human fibrosarcoma HT-1080 and at −91 on MMP-2 in astroglioma cells is mutated respectively." (PMID 23967226, 2013). "A few studies have found high expression of MMP-2 has in high-grade astrocytic tumors in comparison to normal brain tissue." (PMID 34832965, 2021). "CCM has also been demonstrated to inhibit the expression of MMP-2 and -9 in human astroglioma cells." (PMID 25202424, 2014). "Expression of MMP2 and MMP9 was elevated by IFN-γ treatment in a human salivary gland cell line (HSG), but IFN-γ inhibits constitutive MMP-2 expression in human astroglioma cells." (PMID 30622567, 2018). "This RTVP-1 mediated MMP2 secretion facilitates ECM remodelling and influences the invasion of astrocytic tumors." (PMID 24859313, 2014).